SIRT2 (sirtuin 2)
Diseases named in the same sentence as SIRT2 in open-access papers (continued):
Sharing a sentence is not in itself a finding about the gene and the disease.
Parkinson disease (continued). "Genetic ablation of SIRT2 has been shown to have protective effects in models of neurodegenerative disorders such as Huntington’s and Parkinson’s diseases." (PMID 31973227, 2020). "Encouragingly, recent reports of sub-micromolar SIRT2-selective inhibitors also show neuroprotection in a Parkinson’s disease model." (PMID 31973227, 2020). "Inhibition of SIRT2 has been found to be neuroprotective in models of Parkinson’s disease and other neurodegenerative disease contexts." (PMID 32709255, 2020). "Changes in NAD+ metabolism in cells derived from sporadic Parkinson’s disease patients activate SIRT2, which in turn deacetylates α-tubulin, a SIRT2 target." (PMID 31492861, 2019). "For example, the SIRT2 inhibitor AGK2 effectively rescues neurons from α-synuclein-induced neurotoxicity in Parkinson’s disease models." (PMID 30209341, 2018). "Genetic knockout of SIRT2 and small molecule SIRT2 inhibitors both show neuroprotection against the neurotoxicity observed in a Parkinson’s disease cell model and a transgenic mouse model." (PMID 29724067, 2018). "SIRT2 inhibitors are capable of postponing the axon degeneration in Parkinson's disease models due to their presence in cell bodies of neurites and growth cones in axons." (PMID 28197299, 2017). "We further investigated the protective effects of SIRT2 deletion in the chronic MPTP mouse model of parkinsonism." (PMID 28257421, 2017). "ANKLE2 and SIRT2 depletion yield aberrant nuclear morphology also found in Parkinson's disease, progeria and aging." (PMID 27875273, 2016). "SIRT2 inhibition has been shown to have a neuroprotective effect in various Parkinson's disease models, which was linked to the axonal transport rescue through an increase in tubulin acetylation." (PMID 27875273, 2016). "Recently, SIRT2 inhibition has been proposed as a promising therapeutic strategy to achieve neuroprotection in in vitro and in vivo models of Parkinson’s and Huntington’s diseases." (PMID 24860504, 2014). "It was demonstrated that the inhibition of SIRT2 by AGK2 protects against dopaminergic cell death in a Drosophila model of Parkinson’s disease." (PMID 25486244, 2014). "While SIRT2 inhibition can reduce α-synuclein-induced cytotoxicity in cellular and Drosophila models of Parkinson’s disease, decreased SIRT2 activity can lead to apoptosis of C6 glioma cells." (PMID 25486244, 2014). "While beneficial effects of SIRT2 inhibition was shown in neurodegenerative diseases such as Parkinson's and Huntington's disease, the role of SIRT2 in cancer remains controversial." (PMID 24259290, 2013). "A partial rescue of toxicity after genetic knock-down or pharmacological inhibition of SIRT2 has been observed in D. melanogaster models of HD and Parkinson's disease (PD)." (PMID 22511966, 2012). "In contrast, SIRT2 has been reported to promote neurodegeneration in experimental models of Parkinson's disease." (PMID 19116652, 2008). "While it has previously been demonstrated that the inhibition of SIRT2 reduces astrocyte reactivity markers and rescues α-synuclein-mediated toxicity in Parkinson’s Disease models, our study is the first to identify the metabolic step catalyzed by SIRT2 in reactive astrocytes." (PMID 39815261, 2025). "Notably, AGK2 treatment of a Drosophila model of Parkinson’s disease attenuated α-synuclein-mediated toxicity in dorsomedial neurons, implicating Sirt2 as a therapeutic target for inhibition in Parkinson’s disease." (PMID 38474697, 2024). "YKK(ε-thioAc)AM, one of the SIRT2 inhibitors, could inhibit the serum SIRT2 of Parkinson’s disease patients." (PMID 37215138, 2023). "SIRT2 Inhibition has been considered a neuroprotective effect in Parkinson’s disease." (PMID 37215138, 2023). "SIRT2 is essential for LPS-induced microglial cell activation, and inhibiting SIRT2 can reduce microglial cell activation, alleviate neuroinflammation, decrease dopamine neuronal death, and delay Parkinson’s disease neuroinflammation." (PMID 38155866, 2023).
Parkinson disease (continued). "The serum SIRT2 expression was positively correlated to Parkinson’s disease, and the serum SIRT2 level could help to discriminate Parkinson’s disease from atypical Parkinson’s syndrome." (PMID 37215138, 2023). "The scaffolds of 3-(N-arylsulfamoyl) benzamide and 5-((3-amidobenzyl) oxy) nicotinamides may provide other options to explore more SIRT2 inhibitors as a potential therapy for Parkinson’s disease." (PMID 35625059, 2022). "The SIRT2 inhibitor AGK2 showed a neuroprotective effect in Parkinson’s Disease models." (PMID 34650436, 2021). "Therefore, the inhibition of SIRT2 is a candidate target for the treatment of neurodegenerative diseases, such as Alzheimer’s, Parkinson’s, and Huntington’s diseases." (PMID 34943825, 2021). "To determine whether this reduction was specific to patients with dementia, we analyzed SIRT1 and SIRT2 expression in buffy coat samples from patients with parkinsonism." (PMID 35008438, 2021). "Thus, miR-486-3p, miR3761-5p, and miR-8061 and their regulation of SIRT2 are attractive areas for future study in terms of their etiology and therapeutic use in Parkinson’s and Alzheimer’s diseases." (PMID 34943825, 2021). "The administration of miRNAs, such as miR-212-5p and miR-486-5p, to target SIRT2 could be used as a therapeutic treatment for Parkinson’s disease and cancer." (PMID 34943825, 2021). "Inhibition of SIRT2 in vitro also reduces cholesterol synthesis, which may have positive effects against the progression of both Huntington’s and Parkinson’s disease." (PMID 33806509, 2021). "The role of SIRT2 in the alpha-tubulin deacetylation may be involved in neuropathologies, such as Parkinson’s disease or Alzheimer’s disease." (PMID 34360775, 2021). "Furthermore, the SIRT2 inhibitor AGK alleviated α-synuclein-mediated dopamine neuronal loss in vitro and in a Drosophila Parkinson’s disease model." (PMID 34943825, 2021). "In addition to the miR-212-5p–SIRT2 axis, the regulation of SIRT2 by other miRNAs in Parkinson’s disease has been reported." (PMID 34943825, 2021). "Furthermore, miR-212-5p prevents dopaminergic neuron death in the pathogenesis of Parkinson’s disease by inhibiting sirtuin 2 (SIRT2) expression and activity." (PMID 33760887, 2021). "SIRT2 reduces the formation of α-synuclein aggregates in Parkinson’s disease." (PMID 30871086, 2019). "Moreover, sirtuin 2 is reported to exacerbate alpha-synuclein toxicity in models of Parkinson’s disease." (PMID 30364275, 2018). "Interestingly, SIRT2 emerged as a potential culprit in Parkinson disease (PD) pathology, as we showed that SIRT2 modulates α-synuclein (aSyn) aggregation and toxicity." (PMID 28257421, 2017). "Next, we evaluated whether genetic inhibition of sirtuin 2 could prevent the deleterious effects of alpha-synuclein in vivo and found that, in two different models of Parkinson disease, deletion of sirtuin 2 was neuroprotective." (PMID 28257421, 2017). "Our data therefore suggest that strategies aimed at decreasing sirtuin 2 activity might prove valuable therapeutic avenues for intervention in Parkinson disease and other synucleinopathies." (PMID 28257421, 2017). "SIRT2 plays an important role for neurocognitive ability in adult, middle-aged mice and few studies have demonstrated that inhibition of SIRT2 reduces the aggregation of α-synuclein via modulation of tubulin activity to mitigate Parkinson's toxicity." (PMID 27070252, 2016). "In fact, blocking SIRT2 counteracted alpha synuclein toxicity in Parkinson’s disease models." (PMID 24860504, 2014). "Specifically, SIRT2 is reportedly increased upon damage to the spinal cord in rat following a proteomic approach, while its pharmacological or genetic inhibition protects against neurotoxicity in models of Parkinson's disease." (PMID 22490786, 2012).
Parkinson disease (continued). "Sirt2 inhibition could thus be an approach for therapy of this and other neurodegenerative diseases, such as Parkinson's disease, where Sirt2 inhibition was shown to prevent death of dopaminergic cells." (PMID 21937767, 2011). "At all events, increased SIRT2 expression or activity delays the toxic effects induced by α-synuclein, the protein that forms insoluble aggregates in several age-onset pathologies including Parkinson’s disease." (PMID 27713233, 2009). "Given the multiple roles played by SIRT2 in regulating physiological and pathological signal transduction, it can be considered as a key target for the treatment of different illnesses, including neuroinflammation and Parkinson’s disease, as well as cancer and CVD." (PMID 38396635, 2024). "There is compelling evidence to support the fact that SIRT1 and SIRT2 are shuttled between the nucleus and cytoplasm and perform context-dependent functions in neurodegenerative diseases including Alzheimer’s disease (AD), Parkinson’s disease (PD), and Huntington’s disease (HD)." (PMID 33597872, 2020). "Compound 11 may be competitive against both substrate and NAD+; 11 and 12 can significantly reverse the cytotoxicity induced by α-synuclein aggregation in SH-SY5Y cells, which laid the foundation for the research of SIRT2 inhibitors for potential therapy against Parkinson's disease." (PMID 35521274, 2020). "We first tested the accuracy of two machine learning-built models and finally chose to use the random forest to obtain five Parkinson’s disease FRHGs (CISD1, SIRT2, NUPR1, ADAM23 and NEDD4L)." (PMID 38127902, 2023). "Green module was obtained for five Parkinson’s disease FRGs (MAP3K11, SNX4, SIRT2, NUPR1, and ACSL4)." (PMID 38127902, 2023). "The top 5 genes were extracted as FRHGs in Parkinson’s disease (CISD1, SIRT2, NUPR1, ADAM23 and NEDD4L)." (PMID 38127902, 2023). "NAD-dependent protein deacetylase Sirtuin 2 (SIRT2), which regulates several cellular pathways by deacetylating multiple substrates, has been extensively studied in the context of Parkinson’s disease (PD)." (PMID 35443760, 2022). "In the present study, we characterize SIRT2 inhibition activity of the brain-permeable compound AK7 and examine the efficacy of this small molecule in models of Parkinson’s disease, amyotrophic lateral sclerosis and cerebral ischemia." (PMID 25608039, 2015). "The SIRT2 inhibitor AK-7 has been shown to ameliorate the deterioration of Parkinson’s disease and Huntington’s disease, but not amyotrophic lateral sclerosis." (PMID 37684620, 2023). "miR-486-3p targets and downregulates the deacetylase Sirtuin 2 (SIRT2), resulting in decreased α-synuclein-induced toxicity in vitro, and suggesting that miR-486-3p may protect against Parkinson’s disease progression." (PMID 35731367, 2022). "Also, because of the increased acetylated FOXO3a level and decreased Bim expression, SIRT2 knockout mice showed resistance against 1-methyl-4-phenyl-1,2,3,6-tetrahydropyridine (MPTP), which induces neurotoxicity like Parkinson’s Disease." (PMID 34650436, 2021). "Targeting the activity of SIRT2 is beneficial in Parkinson's disease (PD) and Huntington's disease (HD) but not in CMT." (PMID 34053152, 2021). "Relating sirtuin-2 to Arc biology would be an exciting result as inhibition of this KDAC by AK-7 has been found to prevent neurodegeneration in mouse models of Huntington’s, Parkinson’s, and Alzheimer’s diseases." (PMID 29162813, 2017). "Importantly, we found that SIRT2 deletion was protective in both the AAV-mediated model of aSyn expression in the SN and in the chronic MPTP model of parkinsonism." (PMID 28257421, 2017). "Also the inhibition of sirtuin 2 (SIRT2) rescued a-synuclein toxicity and modified inclusion morphology in a cellular model of Parkinson's disease and genetic inhibition of SIRT2 via small interfering RNA similarly rescued a-synuclein toxicity." (PMID 27790141, 2016).
Parkinson disease (continued). "These have not been analysed previously in the context of Parkinson’s disease pathogenesis, in contrast to other sirtuin family members (Sirt1, Sirt2, and Sirt3)." (PMID 27763519, 2016). "Downregulation of SIRT2 has both negative effects, by increasing oxidative stress and necrosis, and positive effects, by protecting from ischemic injury and inhibiting progression of Huntington’s and Parkinson’s diseases." (PMID 33806509, 2021).
breast cancer (61 papers, 2006 to 2026). A primary or metastatic malignant neoplasm involving the breast. "SIRT2‐deficient breast cancer cells exhibit increased acetylation at PKM2 K305, preventing PKM2 tetramerisation and thereby reducing PKM2 enzymatic activity, ultimately altering glucose metabolism and inhibiting tumour growth." (PMID 39778006, 2025). "SIRT2, primarily cytoplasmic and associated with microtubule regulation, modulates breast cancer cell migration, chemotherapy response, and cell cycle progression." (PMID 41471349, 2025). "The TM pseudopeptide demonstrated cytotoxic effects in multiple breast cancer cell lines but had less impact on the growth of normal epithelial cell lines, indicating that breast cancer cells are more susceptible to Sirt2 inhibition." (PMID 38474697, 2024). "Conversely, an upregulation emerged in genes associated with the inhibition of breast cancer progression, including SIRT2, MST1, and ULK1, indicating the therapeutic potential of the peptide." (PMID 38272230, 2024). "In samples collected from the blood of breast cancer patients, the expression of Sirt2 was lower in comparison to healthy individuals, and Sirt2-deficient mice demonstrated decreased TEM cells with increased naïve T-cell levels." (PMID 35887172, 2022). "Meanwhile, accumulating studies have indicated that elevated expression of SIRT2 was also associated with the progression of gastric cancer, hepatocellular carcinoma, and basal-like breast cancer." (PMID 35177983, 2021). "In many human cancers, SIRT2 has been recognized as a tumour suppressor, and an association between mammary tumours, hepatocellular carcinomas and a loss of SIRT2 has been found in mice." (PMID 32697380, 2020). "SIRT2 deficiency promotes breast cancer tumorigenesis and hepatocellular carcinoma tumorigenesis in mice." (PMID 32697380, 2020). "In summary, we have identified an association of SIRT2 with enhanced CD8+ TEM cell differentiation in breast cancer, an event mediated at least in part by activated aerobic oxidation as well as the inhibition of GSK3β acetylation in CD8+ T cells." (PMID 33061819, 2020). "It acts as a tumour suppressor, as SIRT2-knockout mice develop mammary tumours or hepatocellular carcinoma and loss of SIRT2 facilitates tumour formation in a model of skin squamous cell carcinoma." (PMID 27875273, 2016). "Furthermore, lower SIRT2 expression was observed in metastatic samples suggesting that SIRT2 downregulation may be associated with more aggressive phenotype in breast cancer." (PMID 33014852, 2020). "Radiotherapy downregulates SIRT2 levels in breast cancer patients post-treatment, with pre-radiotherapy SIRT2 levels positively correlated with treatment response, suggesting SIRT2 as a potential predictive biomarker." (PMID 41471349, 2025). "TM, a SIRT2 inhibitor, induced the degradation of c-Myc and thus inhibited the growth of breast cancer cells and xenograft models." (PMID 40165290, 2025). "In breast cancer, SIRT2 inhibits the acetylation of GSK3β in CD8(+) effector memory T cells, leading to an increase in the number of effector memory T cells, enhancing the tumour immune response and slowing tumour progression." (PMID 39778006, 2025). "Conversely, in breast cancer stem cells (CSCs), SIRT2 was found to promote the activity of aldehyde dehydrogenase 1A1 (ALDH1A1) via deacetylation, which in turn facilitates breast CSCs activation and self‐renewal." (PMID 39215785, 2025). "Doxorubicin was reported to inhibit SIRT2 and NF-κB p65 phosphorylation in murine breast cancer cells, inducing apoptosis." (PMID 41425553, 2025). "High protein expression of SIRT2 was correlated with poor prognosis in high-grade breast cancer, but the correlation was reversed in intermediate-grade breast cancer." (PMID 40165290, 2025). "In breast cancer cell lines, and specifically in c‐Myc‐driven cancers, 23a displays potent antiproliferative activity and its effects were similar to SIRT2 knockdown." (PMID 39215785, 2025).